DDR1 (discoidin domain receptor tyrosine kinase 1)
Diseases named in the same sentence as DDR1 in open-access papers (continued):
Sharing a sentence is not in itself a finding about the gene and the disease.
kidney disease (9 papers, 2010 to 2022). "Further studies demonstrated that both periostin and DDR1 are involved in the regulation of inflammation and fibrosis, two major processes implicated in the development of renal disease." (PMID 28536691, 2017). "Consistent with the findings in subjects with kidney disease, DDR1 is upregulated in multiple animal models of kidney injury." (PMID 36249782, 2022). "Double knockouts of COL4A3 and either DDR1 or integrin α2 show attenuated kidney disease progression, implicating these receptors as contributors to the pathobiology of Alport glomerular disease." (PMID 35223933, 2022). "Staining performed on kidneys of subjects with human kidney disease as well as the use of DDR1tma1 mice, clearly show upregulation of DDR1 in injured resident cells, such as glomerular and/or tubular cells." (PMID 36249782, 2022). "Overall, these two studies showing some beneficial effects of blocking DDR1 in the context of kidney disease, establish DDR1 as a promising therapeutic target." (PMID 36249782, 2022). "To better understand how DDR1 regulates proinflammatory and profibrotic signaling in kidney disease, we used a model of severe unilateral ischemia/reperfusion (IR) injury followed by delayed contralateral nephrectomy." (PMID 34941574, 2022). "Ideally crossing these mice with genetic models of kidney diseases, or exposing these mice to various models of kidney injury can easily allow the analysis and visualization of renal DDR1 expression and localization at baseline and following injury." (PMID 36249782, 2022). "Two studies targeting the kinase activity of DDR1 in animal models of kidney disease have been reported." (PMID 36249782, 2022). "DDR1 null mice were protected against renal disease as evidenced by decreased proteinuria, glomerular inflammation and fibrosis, and increased survival." (PMID 26880216, 2016). "In the glomerular model of renal disease, we showed that preventive administration of oligodeoxynucleotides (ODNs) to inhibit DDR1 expression protected kidneys with an efficiency close to that of gene deletion." (PMID 26880216, 2016). "Data from studies in the UUO model indicated that DDR1 promotes renal disease through activation of the inflammatory response since macrophages from DDR1-deleted animals displayed impaired migration in response to MCP14." (PMID 26880216, 2016). "We have previously demonstrated that abnormal expression of the Discoidin Domain Receptor 1 (DDR1) is a key factor of renal disease by promoting inflammation and fibrosis." (PMID 26880216, 2016). "Previous work showed that double knockouts of COL4A3 and either DDR1 or integrin α2β1 resulted in attenuated kidney disease progression in the autosomal Alport mouse model, clearly implicating aberrant DDR1 and/or α2β1 signaling in Alport glomerular pathogenesis." (PMID 35223933, 2022). "DDR1-null mice are protected from the development and/or progression of kidney disease following injury, clearly suggesting that upregulation of DDR1 observed in animal models of kidney injury and subjects with kidney disease contributes to kidney injury." (PMID 36249782, 2022). "In conclusion, DDR1 inhibition represents an attractive therapeutic option for kidney diseases." (PMID 34941574, 2022). "Due to the low dose used, whether DDR1 inhibitors can be used as prophylactic or therapeutic drugs in kidney disease, needs to be better evaluated." (PMID 36249782, 2022). "Recent studies have demonstrated DDR1 as an important mediator in renal diseases." (PMID 28536691, 2017). "If this is also confirmed in vivo in the disease context, the cleaved ectodomain of DDR1 could be detectable and usable as a plasma or urine biomarker in renal diseases." (PMID 28536691, 2017). "In this context, both periostin and DDR1 may represent potential targets for therapy of renal disease." (PMID 28536691, 2017). "In conclusion, DDR1 appears as an interesting target for therapy of renal disease." (PMID 26880216, 2016).
kidney disease (continued). "The present study investigates whether blocking the expression of DDR1 after the initiation of renal disease can delay or arrest the progression of this pathology." (PMID 26880216, 2016). "Although AON seems to be a promising approach in dampening DDR1-mediated deleterious effects in mouse models of kidney diseases, whether downregulating DDR1 expression is a feasible treatment option for patients with kidney disease remains to be determined." (PMID 36249782, 2022). "Thus, analysis of cleaved DDR1 in the urine and/or plasma of subjects affected by kidney disease may enable the identification of fast progressors who could benefit from anti-DDR selective therapy." (PMID 36249782, 2022). "Interestingly DDR1 activation is linked to lipotoxicity, which may partially explain why deletion of DDR1 in Alport mice slows kidney disease progression." (PMID 35223933, 2022). "Using experimental models of renal disease, we identified and studied two promising candidates: periostin, a matricellular protein with high expression in bone and dental tissues, and discoidin domain receptor 1 (DDR1), a transmembrane collagen receptor of the tyrosine kinase family." (PMID 28536691, 2017). "Future studies should concentrate on the role of ITGA2 in renal disease and on the possible balancing role of both ITGA2 and DDR1." (PMID 20860797, 2010). "The availability of mice lacking DDR1 has been instrumental in studying the role of this receptor in the initiation and progression of kidney disease." (PMID 36249782, 2022). "Our team has recently identified two novel mediators of renal disease which may serve as promising biomarkers and/or targets for therapy of CKD: periostin and discoidin domain receptor 1 (DDR1)." (PMID 28536691, 2017). "In contrast to DDR1, whether and where DDR2 expression is upregulated in subjects with kidney disease has not been investigated." (PMID 36249782, 2022).
infection (6 papers, 2011 to 2024). The state of being infected such as from the introduction of a foreign agent such as serum, vaccine, antigenic substance or organism. "The protein results also suggested that DOX induced the DDR1 knockdown and overexpression after cell infection with corresponding lentivirus." (PMID 39567474, 2024). "DDR1 expression in SW620 cells increased the transcript levels of MYC, FRA1, and JUN compared with control (mock infection)." (PMID 29438985, 2018). "To corroborate DDR1 role in nilotinib mechanism of action, we analysed cell invasion in SW620 cells that overexpressed or not (mock infection) DDR1." (PMID 29438985, 2018).
neurodegenerative disease (4 papers, 2023 to 2024). A disorder of the central nervous system characterized by gradual and progressive loss of neural tissue and neurologic function. "Discoidin Domain Receptor 1 (DDR1) is a tyrosine kinase cell surface receptor that is activated by collagen and upregulated in neurodegenerative diseases." (PMID 36945656, 2023). "As Ddr1 exerts a positive effect on the remyelination process, it could be developed as a potential drug target for promoting myelin repair in neurodegenerative diseases." (PMID 37373466, 2023).
neurological diseases (3 papers, 2021 to 2023). "DDR1 plays a role in neurological disorders during the autophagy process." (PMID 38071340, 2023). "Seven of these proteins have cis-acting pQTLs that colocalise with or are causal for neurological diseases: DDR1, IL12, NEP, CD33, DPEP1, GPNMB, and LEPR." (PMID 34857772, 2021). "Regarding the possible translation of these observations, Fowler and colleagues suggested that DDR1 could be a therapeutic target for neurological diseases." (PMID 34323026, 2021).
adenocarcinoma (2 papers, 2007 to 2022). A common cancer characterized by the presence of malignant glandular cells. "Laser capture microdissection analyses revealed that DDR1 mRNA expression was mainly attributable to adenocarcinoma compared to stromal cells." (PMID 35205677, 2022). "In this work, we showed that DDR1 expression was higher in adenocarcinoma cells than in normal colonic epithelium." (PMID 35205677, 2022).
hematologic cancers (2 papers, 2022 to 2023). "Clinical trials for LAIR-1, LILRB4 and DDR1 in solid and hematologic cancers." (PMID 37662958, 2023).
connective tissue diseases (1 paper, 2016). "Therefore, blocking DDR1 could represent a novel therapeutic strategy in these diseases and other connective tissue diseases driven by Th17 cells." (PMID 27391444, 2016).
psychiatric disorder (1 paper, 2024). A disorder characterized by behavioral and/or psychological abnormalities, often accompanied by physical symptoms. "Regarding the involvement of DDR1 in psychiatric disorders, our results indicate that DDR1 transcript expression is more altered in SCZ than in BD." (PMID 38395959, 2024). "Altogether, our results suggest that DDR1 expression might be altered in SCZ and BD via the proliferation of astrocytes and OPCs, suggesting that these processes are relevant in psychiatric disorders." (PMID 38395959, 2024). "However, a comprehensive description of each DDR1 transcript coexpression network in human brain tissue and, especially, in psychiatric disorders has not yet been performed." (PMID 38395959, 2024).
skeletal dysplasia (1 paper, 2022). Any Mendelian diseases that affects growth and development of the skeleton. "Osteoblast-specific DDR1 deletion in the early developmental stage resulted in postnatal skeletal dysplasia." (PMID 36140274, 2022). "We previously reported that the osteoblast-specific deletion of DDR1 during the developmental stage reduced the osteoblast differentiation and exhibited skeletal dysplasia." (PMID 36140274, 2022).
DDR1 also shares sentences with these, for which no sentence is quoted: lung squamous cell carcinoma (4 papers); renal cell carcinoma (4); rheumatoid arthritis (4); breast (3); fibrosis (3); head and neck cancer (3); hypertensive nephropathy (3); brain tumor (2); colorectal adenocarcinoma (2); esophageal cancer (2); Insulin resistance (2); metastatic cancer (2); multiple sclerosis (2); Pan (2); prostate adenocarcinoma (2); aneurysm (1); Anxiety (1); Artery Disease (1); Arthritis (1); breast adenocarcinoma (1); bronchioloalveolar carcinoma (1); Burkitt lymphoma (1); cholangiocarcinoma (1); chordoma (1); clear cell carcinoma (1); cognitive decline (1); Crohn disease (1); cutaneous squamous cell carcinoma (1); depression (1); diabetic nephropathy (1).
A further 44 diseases each share a sentence with DDR1 in 1 paper.